RN7SL36P (RNA, 7SL, cytoplasmic 36, pseudogene)
Gene: Miscellaneous RNA gene on chromosome 3 (195,146,728 to 195,147,003, reverse strand). Ensembl gene ENSG00000244314.
Homologues: Orthologues: chimpanzee Metazoa_SRP (99% identical), macaque Metazoa_SRP (88% identical), dog Metazoa_SRP (73% identical). Paralogues in human: RN7SL1 (84% identical), RN7SL2 (83% identical), RN7SL3 (83% identical), RN7SL709P (82% identical), RN7SL478P (82% identical), RN7SL197P (81% identical), RN7SL220P (81% identical), RN7SL45P (81% identical), RN7SL411P (81% identical), RN7SL630P (81% identical), RN7SL664P (81% identical), RN7SL91P (81% identical), and 703 more.